AQP1 (aquaporin 1 (Colton blood group))
Diseases named in the same sentence as AQP1 in open-access papers (continued):
Sharing a sentence is not in itself a finding about the gene and the disease.
Polyuria (11 papers, 2005 to 2022). An increased rate of urine production. "Mice with AQP1 deficiency have been observed to be characterized by polyuria, indicating that AQP1 plays a vital role in hyperpermeability." (PMID 35721542, 2022). "AQP1 deletion is associated with a variety of abnormalities including polyuria, polyhydramnios, cataract, cardiovascular homeostasis disorder, angiogenesis anomaly, pain perception impairment, and neuroinflammation." (PMID 31023968, 2019). "Given the appropriate localization of all transporters studied and the phenotype of the CAII-deficient mice, the most likely explanation for polyuria in the null animals is thus reduced water reabsorption from the TDL through AQP1." (PMID 29354070, 2017). "In one study, polyuria and the inability to concentrate their urine has been reported in AQP-1-deficient mice." (PMID 29708187, 2017). "In vitro experiments in mouse kidneys showed that the loss of AQP1 may reduce the reabsorption of water by the descending branch of the medullary canal, leading to polyuria in mice." (PMID 32190088, 2020). "In many forms of renal disease, a reduced water reabsorption in the kidney is manifested, which correlates with reduced expression of various AQPs, including AQP1, and AQP1-deficient mice typically show polyuria as they are unable to concentrate their primary urine." (PMID 29772789, 2018). "Moreover, endotoxemia can induce more severe tubular injury in AQP1-null mice than in wild-type mice, which is characterized by polyuria." (PMID 35280255, 2021). "According to the data obtained from AQP-KO mice studies, AQP1 inhibitors may be a diuretics for treatment of renal diseases, whereas AQP1 induction might be applied to treat polyuria in humans in the further." (PMID 31023968, 2019). "Notably, AQP-1, -2 and -3 were reported to be downregulated in experimental models of acute renal injury, and treatment strategies that reduced acute renal injury and polyuria also normalized AQPs expression." (PMID 29772789, 2018). "In mice lacking expression of the AQP1 gene there is polyuria, and failure to be able to concentrate urine normally, and a similar urinary concentrating defect is seen in the rare humans who lack AQP1." (PMID 15888206, 2005).
xerostomia (10 papers, 2014 to 2025). Dryness of the mouth resulting from reduced salivary secretion. "AQP1 gene therapy has emerged as one of the most promising approaches for treating radiation-induced xerostomia." (PMID 40733067, 2025). "Long-term clinical data support the safety and efficacy of aquaporin-1 (AQP1) gene therapy for radiation-induced xerostomia." (PMID 40733067, 2025). "Direct introduction of an AQP1 expressing AAV vector into salivary glands demonstrated favorable clinical trial results where participants experienced a subjective decrease in xerostomia symptoms." (PMID 33255850, 2020). "A recent clinical trial has advocated the safety of using AQP1 gene therapy for the management of xerostomia patients." (PMID 27834914, 2016). "Two decades after of this discovery, the first human trials of adenoviral-mediated transfer of AQP1 cDNA for radiation-induced salivary hypofunction are showing subjective improvement in xerostomia." (PMID 26630491, 2015). "As AQP1 probably plays a crucial role in saliva secretion in humans, these findings may lead to a novel strategy for treating xerostomia such as that experienced in Sjögren's syndrome." (PMID 29321959, 2018). "However, the use of AQP1 gene therapy for the management of radiotherapy related xerostomia may involve a few challenges such as prevention of host immune reaction and repeated administrations throughout the course of treatment." (PMID 27834914, 2016).
edema (9 papers, 2014 to 2024). An abnormal accumulation of fluid beneath the skin, or in one or more cavities of the body. "The aim of the present study was to test the hypothesis that imbalanced AQP1 expression may be one of the pathogenic mechanisms for hyperoxic lung injury and pulmonary edema at the cellular level." (PMID 25009607, 2014). "Among these, AQP1 and AQP5 are the most important pulmonary aquaporins, and their overexpression is proven to be associated with interstitial edema in severe hypothermia." (PMID 38611652, 2024). "AQP1 mainly transports fluid in interstitial lung and is closely related to pulmonary edema." (PMID 31231624, 2019). "As a result, we hypothesized that AQP1 might be involved in pulmonary edema induced by FES." (PMID 27455237, 2016). "There are no previous reports describing the effects of AQP1 in pulmonary edema induced by fat embolism syndrome." (PMID 27455237, 2016). "AQP1 facilitates the development of hydrostatic pulmonary edema but has no involvement in the active reabsorption of intra-alveolar fluids, and thus AQP1 gene deletion is associated with a 90% reduction in endothelial permeability and secondary pulmonary interstitial edema development." (PMID 38611652, 2024). "Furthermore, molecular pathological analysis of post-traumatic alveolar injury and systemic responses affecting pulmonary edema, including AQP1 and APQ5 mRNA, expression of AQP1 in lung tissue was significantly higher in subacute sharp force injury than in the other groups." (PMID 34977094, 2021).
gastric cancer (9 papers, 2018 to 2025). A primary or metastatic malignant neoplasm involving the stomach. "In vitro loss- of function assays revealed that interference of AQP-1-suppressed gastric cancer proliferation, migration and invasion." (PMID 33209198, 2020). "The role of AQP-1 in RAS associated carcinogenesis of gastric cancer and the underlying mechanisms are poorly understood." (PMID 33209198, 2020). "In gastric cancer, high level of AQP1 in tumor cells and tumor vessels was associated with the development and promotion of gastric tumors and lymphatic metastasis." (PMID 29678898, 2018). "In addition to the close involvement of AQP-1 in cancer progression, the downstream signaling pathways were then implicated in gastric cancer." (PMID 33209198, 2020). "The data revealed that the expression of ALKBH1 was consistently higher than the other two gastric cancer biomarkers, AQP1 and PECAM1, across all 10 clusters." (PMID 38317214, 2024). "In conclusion, we showed that AQP-1 demonstrated oncogenic effects on gastric cancer via GRB7-mediated Ras/ERK activation." (PMID 33209198, 2020). "We first demonstrated quantitative real-time polymerase chain reaction analysis and found up-regulation of AQP-1 in gastric cancer cell lines." (PMID 33209198, 2020). "The functional involvement of AQP-1 in cell apoptosis of gastric cancer needs to be further studied." (PMID 33209198, 2020). "The influence of AQP-1 on epithelial–mesenchymal transition and stemness properties of gastric cancer is also needed for further investigation." (PMID 33209198, 2020). "Firstly, up-regulation of AQP-1 in gastric cancer cell lines indicated a potential role of AQP-1 in gastric cancer." (PMID 33209198, 2020). "Results in this study showed that phosphorylation of GRB7 were inhibited by knockdown of AQP-1, suggesting that Aquaporin-1 facilitates proliferation and invasion of gastric cancer cells via GRB7-mediated ERK and Ras activation." (PMID 33209198, 2020). "Here, the expression levels of AQP-1 in gastric cancer cells were firstly detected, and hereafter, the impact of AQP-1 on tumor progression of gastric cancer was then determined." (PMID 33209198, 2020). "Subsequently, high AQP1 mRNA expression both in male and female was also correlated to poor OS in all the gastric cancer patients including intestinal and diffuse types." (PMID 29678898, 2018). "AQP1 could facilitate proliferation and invasion of gastric cancer cells via GRB7-mediated ERK and Ras activation." (PMID 36803413, 2023). "Therefore, other downstream effector signaling pathways of RAS should also be investigated in AQP-1-mediated gastric cancer." (PMID 33209198, 2020). "Moreover, lower cell viability was discovered in AGS and MKN45 cells transfected with siAQP1 compared cells transfected with siNC, suggesting that interference of AQP-1 inhibited cell proliferation of gastric cancer." (PMID 33209198, 2020). "This study aims to investigate the pathophysiological roles of AQP-1 in gastric cancer." (PMID 33209198, 2020). "A significantly up-regulation of AQP-1 in gastric cancer cell lines, including HGC-27, MKN74, MKN45, AGS, compared to human gastric epithelium cell line (GES-1) was verified by qRT-PCR, suggesting a potential correlation between AQP-1 and gastric cancer progression." (PMID 33209198, 2020). "The present study suggested that AQP-1 might serve as a new potential therapeutic option in gastric cancer treatment through gene silence of AQP-1, AQP-1 target inhibitors or monoclonal AQP-1 specific antibody." (PMID 33209198, 2020). "Moreover, migration and invasion of gastric cancer cells were also suppressed by the interference of AQP-1." (PMID 33209198, 2020). "Although AQP-1 was reported to be expressed in gastric cancer cells, whether AQP-1 demonstrates a cancer-promoting role in gastric cancer remains to be investigated." (PMID 33209198, 2020).
gastric cancer (continued). "Cell migration and invasion were also suppressed by the interference of AQP-1 in AGS and MKN45 cells, indicating that AQP-1 may account for the malignant phenotypes of gastric cancer." (PMID 33209198, 2020). "Protein levels of AQP1 similarly were correlated with poor outcomes, high rates of recurrence and invasiveness in other cancers, including prostate adenocarcinoma, biliary tract carcinoma and gastric cancer." (PMID 32679804, 2020). "In which, we revealed AQP3, AQP9, and AQP11 mRNA expression were associated with improved OS in all gastric cancer patients especially with intestinal subtypes, whereas AQP0, AQP1, AQP4, AQP5, AQP6/2L AQP8, and AQP10 mRNA expression were associated with poor OS in all gastric cancer patients." (PMID 29678898, 2018). "Moreover, we observed that increased AQP1 mRNA expression was significantly associated with higher mortality rate in stages I and III gastric cancer patients." (PMID 29678898, 2018). "This comparison of tumor and adjacent non-tumor tissues suggested that the dysregulation of AQP1 was associated with tumorigenesis in gastric cancer." (PMID 29678898, 2018). "Similarly, high expression of AQP3 and AQP9 mRNA revealed improved OS in female patients, whereas AQP0, AQP1, AQP6/2L and AQP8 were associated with poor OS in gastric cancer." (PMID 29678898, 2018). "AQP-1 may be a potential avenue for pharmaceutical research in gastric cancer." (PMID 33209198, 2020). "However, the tumorigenic mechanism of AQP-1 on gastric cancer is yet to be found." (PMID 33209198, 2020). "Therefore, AQP-1 silence could inhibit gastric cancer progression through inactivation of RAS/ERK pathway." (PMID 33209198, 2020). "Results in the present study showed that knockdown of AQP-1 decreased protein expression of PCNA and MCM2 in gastric cancer cells, suggesting the anti-proliferative role of AQP-1 silence in gastric cancer." (PMID 33209198, 2020). "In addition, AQP1 and AQP2 mRNA expression in gastric cancer patients with HER2 negative gene were associated with unfavorable OS." (PMID 29678898, 2018). "In addition, AQP10 and AQP5 mRNA expression with positive HER2 and AQP1 and AQP2 mRNA with negative HER2 were associated with poor survival in gastric cancer patients." (PMID 29678898, 2018).
ischemia (9 papers, 2015 to 2024). A hypoperfusion of the BLOOD through an organ or tissue caused by a PATHOLOGIC CONSTRICTION or obstruction of its BLOOD VESSELS, or an absence of BLOOD CIRCULATION. "In a rodent testicular ischemia–reperfusion model the increase in AQP1 expression was closely linked to testicular edema after reperfusion." (PMID 36835026, 2023). "It is well known that ischemia–reperfusion causes alteration of AQP1 and AQP4 in the retina." (PMID 32024231, 2020). "In the literature there are several references, mostly on traumatic ischemia models, linking increased AQP1 expression with edema." (PMID 36835026, 2023). "Ischemia reperfusion of lung tissue increased AQP1 expression, and AQP1 knockout severs lung injury and impairs its resolution after ischemia reperfusion." (PMID 30397774, 2019). "Therefore, it is possible that HIF-1α may be induced by ischemia, resulting in increased microvascular permeability and AQP1-dependent myocardial edema." (PMID 26348407, 2015). "In the cardiovascular system AQP1, AQP4, AQP7, and AQP9 are expressed in endothelial cells, vascular smooth muscle cells, and cardiac tissue which all play a vital role in the development and progression of pathologies such congestive heart failure, ischemia, hypertension, and angiogenesis." (PMID 30555637, 2018).
pulmonary hypertension (9 papers, 2018 to 2025). Increased pressure within the pulmonary circulation due to lung or heart disorder. "Genetic variants of aqp1 have been found to be over-represented in heritable pulmonary arterial hypertension patients." (PMID 35163313, 2022). "Studies on various hypoxia‐induced pulmonary hypertension (HPH) rodent models have demonstrated the role of AQP1 in the proliferation and migration of PASMCs." (PMID 41159679, 2025). "According to the pulmonary hypertension gene curation expert panel of pulmonary hypertension of ClinGen, the association of BMPR2, KCNK3, KDR, SMAD9, and TBX4 and PH is definitive, GDF2 is strong, and AQP1 has a limited disease relationship." (PMID 35627312, 2022). "Nevertheless, in 2017 and in 2019, two studies in cell cultures of the hypoxia-induced pulmonary hypertension mouse models determined that AQP1 knockout reduced proliferation and migration potential, and increased proliferation in PASMCs and PAECs." (PMID 35627312, 2022). "We found that elevated levels of AQP1 in PASMCs from pulmonary hypertensive rats were necessary for resistance to apoptosis and that some level of apoptosis resistance could be conferred simply by increasing expression of AQP1 in PASMCs from control rats." (PMID 39175041, 2024). "AQP1 has also been shown to play a role in pulmonary hypertension (PH)." (PMID 36246134, 2022). "Risk factors such as pulmonary hypertension have been correlated with increased AQP1 levels; conversely, cases of established pulmonary hypertension could be restored by AQP1 silencing in a mouse model." (PMID 35163313, 2022). "Hypoxia-induced pulmonary hypertension which upregulated AQP1 was reversed by targeting this AQP." (PMID 36246134, 2022). "In this study, we used the SU5416 plus hypoxia (SuHx) rat model of severe pulmonary hypertension, which mimics many of the features of human PAH, to determine whether AQP1 levels were altered in PASMCs and MVECs and contributed to a hyperproliferative/hypermigratory phenotype." (PMID 34975522, 2021).
Alzheimer disease (8 papers, 2014 to 2025). A progressive, neurodegenerative disease characterized by loss of function and death of nerve cells in several areas of the brain leading to loss of cognitive function such as memory and language. "Changes in levels of AQP1 and AQP4 expression were associated with the accumulation of amyloid beta in the brain of people with Alzheimer’s disease and PD." (PMID 41026459, 2025). "For instance, AQP1 interacts with the amyloid precursor protein, which can upregulate AQP1 expression in Alzheimer’s disease patients’ brains." (PMID 39941100, 2025). "In the networks, AQP1 is one of the most significant genes, and we also noticed that previous research showed that AQP1 silencing attenuates the cognitive impairment in Alzheimer disease (AD) through activation of the Wnt signaling pathway." (PMID 35601501, 2022). "AQP1 channels in the choroid plexus facilitate cerebrospinal fluid production and are up-regulated in reactive astrocytes in pathological conditions including Alzheimer’s disease (AD)." (PMID 38451099, 2024). "Moreover, APP increased AQP1 expression in brains from patients with Alzheimer’s disease through an epigenetic mechanism and AQP1 overexpression reduced Aß production arising from APP cleavage by inhibiting the binding between ß-secretase (BACE1) and APP." (PMID 36077012, 2022). "The evidence supporting the role of Aqp1, or aquaporin 1, in hippocampal development is less clear, however; it has been shown in Aqp-/- mutants that neuron excitability is diminished; it has also been shown that Aqp1 expression is higher than normal in patients with Alzheimer’s disease (AD)." (PMID 24886704, 2014). "The aberrant changes of AQP1 and AQP4 have been repeatedly observed in the brains of Alzheimer disease (AD)." (PMID 31814527, 2019). "The aberrant changes of AQP1 and AQP4 have been observed in the brains of Alzheimer disease (AD)." (PMID 31814527, 2019).
breast tumors (8 papers, 2015 to 2024). "AQP1 is highly expressed in mouse models of breast tumour, and AQP1 deficiency in such models decreased the number of lung metastases." (PMID 31374984, 2019). "AQP1(+/+) MMTV-PyVT mice developed large breast tumors with total tumor mass tumor masses, which were greatly reduced in AQP1(−/−) MMTV-PyVT mice." (PMID 35847914, 2022). "Higher levels of AQP1 expression in breast tumours have been correlated with a triple negativity, poorer prognosis of the disease and higher tumour grade." (PMID 31374984, 2019). "Animal studies show that AQP1 is highly expressed in mouse breast tumor, and AQP1-null mice show impaired angiogenesis." (PMID 30678106, 2019). "Furthermore, considering the importance of AQP1 in angiogenesis and the invasiveness of tumors, together with evidence of survival benefit from clinical trials, the selectivity of Rg3 in targeting AQP1 in metastatic breast tumors should be studied." (PMID 30678106, 2019). "This suggests that Rg3 targeting AQP1 could also be relevant in breast tumors." (PMID 30678106, 2019). "Similarly, AQP1 gene deletion correlated with reduced VEGF receptor expression in mouse primary breast tumor cells, and knockdown of AQP1 in human retinal vascular endothelial cells with concurrent inhibition of VEGF caused an additive inhibition of hypoxia-induced angiogenesis." (PMID 29922644, 2018). "Breast tumors of basal-like TNBC subtype and advanced breast tumors have higher levels of AQP1 expression compared to normal tissues." (PMID 30678106, 2019). "However, application of VEGF-neutralizing antibodies did not alter AQP1 expression, and levels of VEGF in primary breast tumors were not different between AQP1-null and wild-type mice, supporting the idea that VEGF is regulated independently of AQP1 expression or activity." (PMID 29922644, 2018).